TGFB1 (transforming growth factor beta 1)
Diseases named in the same sentence as TGFB1 in open-access papers (continued):
Sharing a sentence is not in itself a finding about the gene and the disease.
hemorrhagic stroke (5 papers, 2017 to 2025). A stroke caused by a bleed on the brain. "Another potential confounder in our study is that all patients suffered one or more hemorrhagic strokes before death, which influences TGFβ1 expression." (PMID 28557134, 2018).
IgG4-related disease (5 papers, 2009 to 2025). "Currently, fibrosis of IgG4-related disease is thought to be induced by profibrotic cytokines such as transforming growth factor beta 1 (TGFB1), interleukin 1 beta (IL1B) and interferon gamma (IFNG), which are secreted by regulatory T cells (Tregs) and CD4-positive cytotoxic T cells." (PMID 29439708, 2018). "Our results suggested the profibrotic cytokines TGFB1, IL1B and IFNG induce fibrosis and that Tregs might produce some of these cytokines in IgG4-related thymitis as well as in the other affected lesions of IgG4-related disease." (PMID 29439708, 2018).
lentivirus infection (5 papers, 2015 to 2023). Virus diseases caused by the Lentivirus genus. "TGFβ1-induced COL1A2, PAI-1, and CTGF mRNA levels were also partially inhibited by shSET7/9 lentivirus infection, whereas no significant increase and decrease induced by TGFβ1 and shSET7/9, respectively, was observed in the GCD2-homozygous cells." (PMID 26553048, 2015).
memory impairment (5 papers, 2018 to 2026). "Importantly, restoration of astrocytic morphology and synaptogenic function through transforming growth factor beta 1 (TGF‐β1) treatment was sufficient to rescue Aβ‐induced synaptic loss and memory impairment." (PMID 41591255, 2026).
Moyamoya disease (5 papers, 2009 to 2022). Moyamoya disease (MMD) is a rare intracranial arteriopathy involving progressive stenosis of the cerebral vasculature located at the base of the brain causing transient ischemic attacks or strokes. "The upregulation of TGFβ1 has been implicated in the pathogenesis of moyamoya disease." (PMID 23966972, 2013). "Furthermore, TGFβ1 has been associated with increased production of elastin synthase, which is involved in intimal cell proliferation, a hallmark of moyamoya disease." (PMID 23966972, 2013). "However, it is only speculated that the expression of TGFβ1 is related to the pathophysiology of moyamoya disease, and the relationship between TGFβ1 and the collateral is still undetermined." (PMID 35873760, 2022).
neovascular glaucoma (5 papers, 2015 to 2024). "Meanwhile, TGFβ1 is upregulated as a consequence of general wound healing as seen in surgical insult to tissue as well as neovascular glaucoma." (PMID 38391628, 2024). "In our study, patients with neovascular glaucoma that was refractory to treatment showed higher levels of IL-6, TGFβ-1, and VEGF than other PDR patients, which implies that the levels of these three factors are correlated with the severity of PDR." (PMID 26491551, 2015). "Patients in group 3 (those with neovascular glaucoma that was refractory to treatment) had higher levels of IL-6, TGFβ-1, and VEGF compared with patients in PDR group 1 and PDR group 2 (the nonneovascular glaucoma groups)." (PMID 26491551, 2015).
oropharyngeal squamous cell carcinoma (5 papers, 2016 to 2024). "In patients with oropharyngeal squamous cell carcinoma undergoing radiotherapy, the presence of the rs1800470 variant of TGFβ1 may reduce and modify the risk of death and recurrence." (PMID 38793065, 2024).
penile cancer (5 papers, 2019 to 2025). A primary or metastatic malignant neoplasm that affects the penis. "IPA identified potential upstream regulators that explain the transcriptional changes of human penile cancer, which included activated targets by pro-inflammatory factors such as TNF, CSF2, IFNγ, IL1B, and inhibited targets by TGFβ1." (PMID 32358507, 2020).
placental insufficiency (5 papers, 2011 to 2023). Failure of the placenta to deliver an adequate supply of nutrients and oxygen to the fetus. "Moreover, the TGFβ1 gene was identified as a possible contributor gene in placental insufficiency and IUGR." (PMID 37626717, 2023).
skin squamous cell carcinoma (5 papers, 2014 to 2022). A carcinoma arising from the squamous cells of the epidermis. "TGFβ1 exhibits biphasic actions in murine skin squamous cell carcinomas: suppressing early tumor growth but enhancing malignant conversion." (PMID 33256177, 2020).
spindle cell carcinoma (5 papers, 2005 to 2015). "Knockdown of endoglin in transformed keratinocyte cell lines not only enhanced TGFβ1 signaling, induced growth arrest and suppressed tumor formation, but also caused EMT, invasiveness and conversion to spindle cell carcinoma." (PMID 23326666, 2012). "Spindle cell carcinoma are a highly undifferentiated and invasive tumor type in the epidermis thought to result in part from an EMT of SCC cells, dependent on TGFβ1 signaling." (PMID 23326666, 2012).
testis cancer (5 papers, 2017 to 2023). "In humans, single nucleotide polymorphisms in TGFB1 gene are associated with an increased risk of developing testicular cancer." (PMID 37048077, 2023). "Adding to the knowledge of the TGFβ superfamily in testis cancer, TGFβ1 was also significantly higher in testis cancer samples." (PMID 29250030, 2017). "The higher expression of TGFB1 has been reported in several cancers, including testis cancer." (PMID 37048077, 2023).
acute monocytic leukemia (4 papers, 2015 to 2023). Acute monoblastic leukemia (AML-M5), is one of the most common subtypes of acute myeloid leukemia (AML) that is either comprised of more than 80% of monoblasts (AML-M5a) or 30-80% monoblasts with (pro)monocytic differentiation (AML-M5b). "In our analyses, we showed that high TGFB1 expression was more commonly seen in the M4 (acute myleomonocytic leukemia) and M5 (acute monocytic leukemia) FAB subtypes, which agreed favorably with the preferential expression of TGFB1 in monocytes." (PMID 37925591, 2023).
astrocytic tumor (4 papers, 2008 to 2025). A glial tumor of the brain or spinal cord showing astrocytic differentiation. "Therefore, the study aimed was to evaluate variances in the expression patterns of TGFβ1–3 in astrocytic tumors with respect to the degree of malignancy." (PMID 40620718, 2025).
bacterial meningitis (4 papers, 2012 to 2024). Inflammation of the membranes surrounding the brain and spinal cord due to a bacterial infection. "Understanding the regulatory mechanism of TGFβ1-HH cascades in BMECs can contribute to developing new treatment strategies to reduce CNS damage in bacterial meningitis and other CNS infection-related diseases." (PMID 38360663, 2024). "Our work revealed the effect of TGFβ1 antagonism on E. coli-induced BBB immune response and suggested that activation of HH signaling may be a potential protective strategy for future bacterial meningitis therapy." (PMID 38360663, 2024).
chondrodysplasia (4 papers, 2013 to 2023). "The detrimental effects of chondrodysplasia-causing mutations on the TGFβ1 signaling pathway could therefore yield pathological consequences for cartilage development and degeneration and potentially contribute to PSACH and MED disease mechanisms." (PMID 23951406, 2013).
Erythema (4 papers, 2012 to 2025). Redness of the skin, caused by hyperemia of the capillaries in the lower layers of the skin. "However, in patients with small breast volume the TGFB1 SNP was associated with erythema (p = 0.028), whereas the SNP in XPD showed an association in patients with large breast volume (p = 0.046)." (PMID 22537351, 2012).
fetal growth restriction (4 papers, 2018 to 2023). A fetus that does not grow beyond the 10th percentile of conventionally accepted weight for gestational age. "Fetal growth restriction also had separate effects on immune development (lower lymphocyte and helper T cell counts) as well as lower expression of PPARG and TGFB1." (PMID 34684311, 2021).
hip osteoarthritis (4 papers, 2013 to 2025). "Recently, polymorphisms in both TGFB1 and IL-6 have been identified as being significantly associated with hip osteoarthritis in Caucasians." (PMID 28860542, 2017). "The objective was to investigate potential gene-environment interaction between body mass index (BMI) and each of eight TGFβ1 polymorphisms in knee and hip osteoarthritis (OA)." (PMID 23597094, 2013).
mantle cell lymphoma (4 papers, 2019 to 2024). Mantle cell lymphoma is a rare form of malignant non-Hodgkin lymphoma affecting B lymphocytes in the lymph nodes in a region called the ``mantle zone''. "TGFB1 expression was positively correlated with the stromal score in AML, classical Hodgkin lymphoma (CHL), CLL, CML, DLBCL, mantle cell lymphoma (MCL), MDS, MM, pre-B ALL, and T-ALL." (PMID 37925591, 2023).
osteoradionecrosis (4 papers, 2011 to 2023). Necrosis of bone following radiation injury. "Our findings indicated that BRONJ was associated with an impairment in TGFβ1 signaling that was different than that associated with osteoradionecrosis of the jaw." (PMID 21726429, 2011). "For example, osteoradionecrosis has been shown to be associated with increased expression of TGFβ1." (PMID 21726429, 2011). "Furthermore, osteoradionecrosis has been associated with increased TGFβ1 expression." (PMID 21726429, 2011). "The connective tissue-related cells were rarely stained, and TGFβ1 expressing fibroblasts in the fibrous and inflammatory tissue surrounding the bone matrix were less dense than those observed in normal and osteoradionecrosis-related tissue." (PMID 21726429, 2011). "The findings also indicated that impairments in TGFβ1-signaling were different in BRONJ compared to osteoradionecrosis." (PMID 21726429, 2011). "In osteoradionecrosis-related mucoperiosteal tissues, increased TGFβ1 and Smad-2/3, together with radiation-induced Galectin-3 were associated with perpetuation of fibrotic soft tissue remodeling and inhibition of re-epithelization {Cao, 2002 #4522}." (PMID 21726429, 2011). "This study showed that BRONJ-adjacent soft tissue and osteoradionecrosis-related mucoperiosteal tissue had differential impairments in TGFβ1-related signaling." (PMID 21726429, 2011). "Osteoradionecrosis-affected tissues showed upregulation of TGFβ1 and Smad-2/3 expression and suppression of Smad-7; this was the opposite of findings in BRONJ-affected tissues." (PMID 21726429, 2011). "TGFβ1 and Smad-2/3 were significantly decreased (p < 0.032 and p(0.028, respectively) in the BRONJ samples and significantly increased (p < 0.04 and p <0.043, respectively) in the osteoradionecrosis samples compared to normal tissue." (PMID 21726429, 2011). "The labeling index (ratio of TGFβ1 expressing cells/total number of fibrous tissue-related cells) was significantly diminished (p < 0.032) in the BRONJ group and significantly increased (p < 0.04) in the osteoradionecrosis group compared to the control mucoperiosteal tissue." (PMID 21726429, 2011). "In osteoradionecrosis-related mucoperiosteal tissues, the overexpression of TGFβ1 causes an arrest of the EMT process in activated myofibroblasts; conversely, in BRONJ, the lack of TGFβ1 and Smad-2/3 activity attenuated the stimulation of EMT {Schultze-Mosgau, 2004 #2678}." (PMID 21726429, 2011).
prolactinoma (4 papers, 2018 to 2025). "There is a suggestion that sex-related TGFβ1 expression in the pituitary is associated with sex-related differences in PRLomas pathogenesis and could protect males from excessive lactotroph proliferation, PRL secretion and PRLoma development." (PMID 38370355, 2024). "Reduced TGFβ1 activity is a common feature in the development of prolactinoma, studies also found that the recovery of TGFβ1 activity emerges as a novel therapeutic target for the treatment of DA-resistant patients." (PMID 30740089, 2018).
rectal tumors (4 papers, 2017 to 2025). "Conversely, it downregulated EEF1A2 in normal rectum organoids, PDE10A in normal colon organoids, and TGFB1 in rectal tumor organoids." (PMID 32824266, 2020).
retinitis pigmentosa (4 papers, 2021 to 2022). Retinitis pigmentosa (RP) is an inherited retinal dystrophy leading to progressive loss of the photoreceptors and retinal pigment epithelium and resulting in blindness usually after several decades. "Previous studies confirmed that overexpression of TGFB1 in the cones can reduce the cone degeneration caused by retinitis pigmentosa through microglia and ablation of TGFBR2 in retinal microglia lead to the microglia activation and promote the pathological microglial gene expression profile." (PMID 34434927, 2021). "Effect of combinations of Txnip.C247S with Best1-Nrf2 or Tgfb1 on retinitis pigmentosa cone survival." (PMID 33847261, 2021).
rheumatic heart disease (4 papers, 2017 to 2024). An autoinflammatory condition following an infection with Group A Beta Hemolytic Streptococcus (GABHS), in which the heart is attacked by antibodies formed in reaction to a recent GABHS infection. "Additionally, CD4+ T cells and the TGFβ1/MAPK pathway have been identified as contributors to valvular hyperplasia and fibrosis in individuals with rheumatic heart disease." (PMID 39421157, 2024).
sickle cell disease (4 papers, 2018 to 2022). Sickle cell anemias are chronic hemolytic diseases that may induce three types of acute accidents: severe anemia, severe bacterial infections, and ischemic vasoocclusive accidents (VOA) caused by sickle-shaped red blood cells obstructing small blood vessels and capillaries. "In our current model, KCa3.1 blockade using senicapoc, a drug very well tolerated in a phase 3 clinical trial of human sickle cell disease, was highly effective at inhibiting the pro-fibrotic effects of TGFβ1 both in terms of gene transcription, and tissue protein markers of fibrosis." (PMID 29321510, 2018).
skin infection (4 papers, 2019 to 2024). An inflammatory process affecting the skin, caused by bacteria, viruses, parasites, or fungi. "Notably, among them, transforming growth factor beta 1 (TGFβ-1) represents a recruiting signal that attracts neutrophils towards the lesion site, lowering the possibility of the onset of skin infections." (PMID 34209306, 2021).
tongue cancer (4 papers, 2017 to 2025). A malignant neoplasm affecting the tongue. "Ectopic expression of miR-639 in tongue cancer CAL 27 and SCC9 cells considerably inhibited TGFβ (TGFB1; transforming growth factor, β 1)-induced EMT." (PMID 28708091, 2017).
trachoma (4 papers, 2013 to 2017). "Some studies have reported constitutive expression of TGFβ proteins in the conjunctiva, without any difference between trachoma cases and controls, while others have reported stimulation of TGFβ1 in the conjunctiva of trachoma patients." (PMID 28660176, 2017).
urinary tract infection (4 papers, 2017 to 2023). "We also know that a great number of polymorphisms that involve TLRs, CXC receptors, VEGF and TGFβ1 increase the risk of urinary tract infections in both CKD patients and in otherwise healthy ones and UTIs lead to a faster decline in renal function." (PMID 36676673, 2022). "Literature of the last decade has brought results of research indicating a link of TGFβ1 polymorphisms both with urinary tract infections, as well as with VUR." (PMID 27988909, 2017). "Moreover, genetic alterations of vascular endothelial growth factor A (VEGFA) and transforming growth factor beta 1 (TGFβ1) are related to kidney scarring and progressive kidney disease after urinary tract infections, especially those associated with vesicoureteral reflux." (PMID 37893554, 2023). "In many pathologies of the urinary system, including infections of the urinary tract, but also the states of arousal RAAS, there is increased excretion of TGFβ1 in urine." (PMID 27988909, 2017).
vesicoureteral reflux (4 papers, 2017 to 2023). Abnormal flow of urine from the urinary bladder back into the ureters. "Another notable fact is that polymorphisms involving vascular endothelial growth factor A (VEGFA) and transforming growth factor beta 1 (TGFβ1) were related to kidney scarring after UTIs and progressive kidney disease, especially associated with vesico-ureteral reflux." (PMID 36676673, 2022). "The aim of this study was to establish the relationship of selected polymorphisms: 14094 polymorphism of the ACE, polymorphism rs1800469 of TGFβ-1, rs5443 gene polymorphism of the GNB3 and receptor gene polymorphism rs5186 type 1 AGTR1 with the occurrence of the primary vesicoureteral reflux." (PMID 27988909, 2017).
Age-related cataract (3 papers, 2018 to 2023). A type of cataract (opacification of the lens) that forms during the course of aging. "We found that the concentrations of IL-8, MMP-2, MMP-3, MMP-9, TGFβ-1, TGFβ-2, TGFβ-3, SAA, and TNF-α were significantly elevated in JIAU samples compared with the control group (senile cataract patients)." (PMID 29675026, 2018).
anaphylaxis (3 papers, 2019 to 2025). An acute hypersensitivity reaction that occurs from exposure to an allergen. "Glycomacropeptide (GMP), a novel inhibitor of anaphylaxis, can increase the production of TGFβ1, attenuate mast cell activation by allergen, and suppress the secretion of histamine in the rat model of anaphylaxis." (PMID 31597362, 2019). "Given the fact that TGFβ1 confers oral tolerance to food allergens, HDAC2 might act as a negative regulator of allergies and anaphylaxis." (PMID 31597362, 2019).
autoimmune gastritis (3 papers, 2014 to 2024). Inflammation of the body fundic mucosa of the stomach. "In vitro culture using biopsy specimens from patients with autoimmune gastritis revealed higher concentrations of tumor necrosis factor-alpha (TNF-α), IL-15, and transforming growth factor-beta 1 (TGF-β1) compared with those from healthy controls." (PMID 37504250, 2023).
breast fibrosis (3 papers, 2014 to 2021). Breast fibrocystic change characterized by the prominence of fibrotic changes in the parenchyma. "Whilst most reports addressing the impact of TGFβ pathway polymorphisms on side effects of radiotherapy so far are retrospective, a recent study conducted in a prospective fashion highlighted the −509T allele in the promoter region of TGFB1 as a key determinant of breast fibrosis risk." (PMID 34771749, 2021).
Chagas cardiomyopathy (3 papers, 2018 to 2024). A disease of the cardiac muscle developed subsequent to the initial protozoan infection by trypanosoma cruzi. "In agreement with our previous study, we detected Tgfb1 overexpression in the hearts of chronic chagasic mice, which may influence the Chagas cardiomyopathy’s development by modulation of the immune response." (PMID 33804922, 2021).
chronic kidney failure (3 papers, 2007 to 2019). "However, a study reported a significant association of C>T-509 (p = 0.02) SNPs in TGFβ1 gene polymorphisms with chronic kidney failure in European population." (PMID 17428349, 2007).
coagulopathies (3 papers, 2021 to 2023). "Further data analysis and interpretation suggested the involvement of acute activation of TGFβ1, IL1β, and ADORA2A signaling, as well as the increased levels of fibrinogens and fibronectin to block coagulopathies." (PMID 33668155, 2021).
Fuchs endothelial corneal dystrophy (3 papers, 2017 to 2025). Fuchs endothelial corneal dystrophy (FECD) is the most frequent form of posterior corneal dystrophy (see this term) and is characterized by excrescences on a thickened Descemet membrane (corneal guttae), generalized corneal edema, with gradually decreased visual acuity. "While the association of TGFβ1 and IL10 was reported in Fuchs’ dystrophy, our data suggest that these profibrogenic and anti-inflammatory mediators are not dependent by sex phenotype." (PMID 38999352, 2024). "The fact that VEGFA (angiogenic factor), βNGF (neurotrophic factor) and TGFβ1 (anti-inflammatory and profibrogenic factor) were upregulated in Fuchs’ dystrophy but not significantly linked to gender, is in line with previous studies." (PMID 38999352, 2024).
gingival fibromatosis (3 papers, 2021 to 2025). "Exposure of the mutant cells to TGFB1 further upregulated the expression of TGFβ targets suggesting that this pathway could be a central player in the pathogenesis of the ERS gingival fibromatosis." (PMID 34777248, 2021).